GAS5 (growth arrest specific 5)
Diseases named in the same sentence as GAS5 in open-access papers (continued):
Sharing a sentence is not in itself a finding about the gene and the disease.
nephritis (3 papers, 2017 to 2019). Inflammation of renal tissue. "When the patients with SLE were divided into LN and SLE without nephritis, the combination of lnc-DC and GAS5 with AUC 0.712 may server as potential novel biomarkers for distinguishing LN from SLE without nephritis." (PMID 28423570, 2017). "Further evaluation on potential biomarkers showed that GAS5, linc0597 and lnc-DC may specifically identify patients with SLE, the combination of GAS5 and linc0597 provided better diagnostic accuracy; lnc-DC may discriminate LN from SLE without nephritis." (PMID 28423570, 2017). "In conclusion, our results provide novel empirical evidence that GAS5, linc0597 and lnc-DC may specifically identify patients with SLE, the combination of GAS5 and linc0597 could provide better diagnostic accuracy; in addition, lnc-DC may discriminate patients with LN from SLE without nephritis." (PMID 28423570, 2017).
neuroblastoma (3 papers, 2017 to 2019). Neuroblastoma (NB) is the most common solid, extracranial childhood tumor. "Complementation studies of the variants post-knockdown of GAS5 indicated alternate phenotypes, with one variant (FL) considerably enhancing cell proliferation by rescuing cell cycle arrest and the other (C2) driving apoptosis, suggesting a unique role for each in neuroblastoma cancer physiology." (PMID 28035057, 2017). "LncRNAs are involved in many biological processes, with LncRNA-MALAT1 and GAS5 being reported to mediate cell invasion, migration, and apoptosis in human neuroblastoma." (PMID 30285664, 2018). "Our examination of GAS5 in neuroblastoma has revealed robust expression in both MYCN-amplified and non-amplified cell lines." (PMID 28035057, 2017). "Knockdown of GAS5 in neuroblastoma cell lines revealed defects in cell proliferation, apoptosis, and cell cycle arrest." (PMID 28035057, 2017). "In order to better characterize GAS5 in neuroblastoma cells, we decided to clone the lncRNA." (PMID 28035057, 2017). "Together, these data indicate that GAS5 expression has a significant impact on neuroblastoma cell biology and differential expression of its splice variants could act to regulate physiological priorities toward cell proliferation or regulation of apoptosis." (PMID 28035057, 2017). "Given recent discoveries of the presence of lncRNAs relevant to neuroblastoma and various reports of the significance of GAS5 in several cancer systems, we decided to examine if this lncRNA showed promise as a biomarker or possible therapeutic target in this cancer system." (PMID 28035057, 2017). "An examination of MYCN-amplified and non-amplified neuroblastoma cell lines revealed robust expression of GAS5 in both, but with no initial correlation to MYCN expression." (PMID 28035057, 2017). "Our analysis of GAS5 in neuroblastoma indicates it is expressed in both MYCN-amplified and non-amplified cell lines." (PMID 28035057, 2017). "Together, these data indicate that a pattern of differential GAS5 splice variant expression may be present between MYCN-amplified and non-amplified neuroblastoma cell lines." (PMID 28035057, 2017). "In order to determine if there is a correlation between MYCN and GAS5 expression levels in neuroblastoma, 15 neuroblastoma cell lines were screened (6 MYCN-amplified and 9 non-amplified) for both MYCN and GAS5 expression by qRT-PCR, normalized to GAPDH." (PMID 28035057, 2017). "In order to determine the function of GAS5 expression in human neuroblastoma, both MYCN-amplified (IMR-32) and non-amplified (SK-N-AS) cell lines were transfected with two separate GAS5 siRNAs." (PMID 28035057, 2017).
nonalcoholic fatty liver disease (3 papers, 2022 to 2025). "A recent study revealed that the lncRNA growth-arrest specific transcript 5 (GAS5) plays a protective role in nonalcoholic fatty liver disease by acting as a sponge for miR-28a-5p, which subsequently targets MARCH7." (PMID 40307577, 2025). "For instance, in nonalcoholic fatty liver disease (NAFLD), GAS5 acts as a competing endogenous RNA (ceRNA) for miR-28a-5p, which has been demonstrated to promote pyroptosis through MARCH7-mediated NLRP3 activation, thereby exerting a protective effect." (PMID 39941145, 2025).
preeclampsia (3 papers, 2020 to 2023). Preeclampsia is a hypertensive disorder of pregnancy that is characterized by new-onset hypertension with proteinuria presenting after 20 weeks of gestation, and depending on mild or severe forms may initially present with severe headache, visual disturbances, and hyperreflexia. "Although lncRNA Growth Arrest-Specific 5 (GAS5) aberrantly expressed in multiple cancer tissues and is implicated in multiple biological processes of tumor cells, little is known about its role in preeclampsia." (PMID 32194641, 2020). "In the placental tissues of Preeclampsia patients, lncRNA GAS5 expression is elevated, and its level rises as the severity of the disease does as well." (PMID 37745705, 2023). "Our work revealed the different expression of GAS5 in placentas of preeclampsia patients, simultaneously, possibly offered a clue for the further exploration, on the correlation between GAS5 and endothelial injury cascading coagulopathy." (PMID 32194641, 2020). "The expression of GAS5 was elevated in preeclampsia patients’ placentas and demonstrated a correlation with coagulation parameters-TT and fibrinogen, as well as serum protein level." (PMID 32194641, 2020). "Previous work of our research group showed that in GEO Profiles, high throughput sequencing affirmed the high level of GAS5 expressed in human placental tissue and the different expression between preeclampsia and normal pregnancy." (PMID 32194641, 2020). "This is the first report of exploring the role of GAS5 in preeclampsia and expects more subsequent relative researches." (PMID 32194641, 2020). "Thus the relevant mechanism of GAS5 involved the preeclampsia pathogenesis was preliminarily explored." (PMID 32194641, 2020). "GAS5 expression which is found to be decreased in tumor tissues has been proved to increase in preeclampsia placenta in our work firstly, especially with the highest level in early-onset, which is consistent with the pathological feature of insufficient trophoblast invasion." (PMID 32194641, 2020). "Therefore, this research firstly attempted to verify the GAS5 involvement of preeclampsia and the correlation between GAS5 and clinical parameters." (PMID 32194641, 2020). "According to our current work, GAS5 is a novel lncRNA involving in preeclampsia." (PMID 32194641, 2020). "The degree to which lncRNA GAS5 was expressed in Preeclampsia patients was inversely correlated with spiral artery lumen area and positively correlated with spiral artery wall thickness, suggesting that lncRNA GAS5 may be connected to the process of placental spiral artery recasting." (PMID 37745705, 2023). "Thus, we suggested that GAS5 might involve in pregnancy with preeclampsia by influencing the biological functions of trophoblast cells through the regulation of miR-21 and activation of PI3K/AKT signaling pathway and its downstream targets, which may contribute to reveal the nature of preeclampsia." (PMID 32194641, 2020). "Until now, role of GAS5 in preeclampsia has not been reported." (PMID 32194641, 2020).
pulmonary fibrosis (3 papers, 2016 to 2023). Chronic progressive interstitial lung disorder characterized by the replacement of the lung tissue by connective tissue, leading to progressive dyspnea, respiratory failure, or right heart failure. "Lung fibrosis in mice was attenuated by GAS5 overexpression but promoted by GAS5 deficiency." (PMID 36918759, 2023). "Finally, GAS5 overexpression attenuated lung fibrosis in bleomycin-induced mice by regulating the KDM5B/PDGFR α/β signaling pathway." (PMID 36918759, 2023).
schizophrenia (3 papers, 2019 to 2022). A major psychotic disorder characterized by abnormalities in the perception or expression of reality. "However, when comparing data between sexes (males vs. females), GAS5, NEAT1 and OIP5‐AS1 expression levels had a higher and more significant association with schizophrenia in female patients compared to males." (PMID 35040588, 2022). "Recent studies have been carried out on OIP5‐AS1 along with other lncRNAs (FAS‐AS1, PVT1, TUG1, THRIL, NEAT1 and GAS5) due to their involvement in neurodevelopmental and/or neurobiological processes, and their involvement in signalling pathways present in patients with schizophrenia." (PMID 35040588, 2022). "While Gomafu, PINT, GAS5, TCONS_l2_00021339, IFNG-AS1, FAS-AS1, PVT1, and TUG1 are among down-regulated lncRNAs in schizophrenia, MEG3, THRIL, HOXA-AS2, Linc-ROR, SPRY4-IT1, UCA1, and MALAT1 have been up-regulated in these patients." (PMID 34220567, 2021). "Levels of GAS5, NEAT1 and OIP5‐AS1 were generally similar between patients diagnosed with schizophrenia and those negative for schizophrenia." (PMID 35040588, 2022).
steatosis (3 papers, 2020 to 2025). Increased lipid within the cytoplasm of cells. "ROC curve analysis of GAS5 revealed a 3.75-fold change, achieving 100% sensitivity and 83.3% specificity in differentiating steatosis from NASH." (PMID 40868128, 2025). "The 10 most significantly downregulated genes in NAFLD included genes protecting against steatosis (MET) and fibrosis (GAS5), cancer suppression (RBMS1), and genes downregulated in HCC (FNDC3B)." (PMID 40489530, 2025). "In addition, expression of GAS5 did not significantly differ according to the degree of steatosis or inflammation or the presence or severity of NASH in either tissue or plasma." (PMID 32413995, 2020).
urothelial cell carcinoma (3 papers, 2020 to 2022). "Regarding the SNP of GAS5, the GAS5 SNP rs145204276 increases the probability of larger tumor status in urothelial cell carcinoma." (PMID 36011604, 2022).
B-cell lymphoma (2 papers, 2016 to 2019). "A chromosomal translocation mutation implicated in B-cell lymphoma was linked to the GAS5 lncRNA; the mutation causes fusion of the GAS5 transcript to the BCL6 gene." (PMID 31379598, 2019).
benign prostatic hyperplasia (2 papers, 2015 to 2025). A non-cancerous nodular enlargement of the prostate gland. "In this study, we aimed to evaluate the diagnostic utility of exosomal lincRNA-p21 and GAS5 levels in individuals with benign prostatic hyperplasia (BPH) and PCa." (PMID 25999983, 2015).
bipolar disorder (2 papers, 2023). A disorder of the brain that causes unusual shifts in mood, energy, activity levels and the ability to carry out day-to-day tasks. "In brief, the result of this study provided clues for an association between dysregulation of FOXD3-AS1 and GAS5 lncRNAs and bipolar disorder." (PMID 37620425, 2023). "Down-regulation of GAS5 in bipolar disorder compared with healthy controls is reported in the literature, and the trend shown in our study is in agreement with the data already collected by the authors." (PMID 37761918, 2023).
brain cancer (2 papers, 2018 to 2020). A primary or metastatic malignant neoplasm affecting the brain. "In this study, we measured the expression of two ncRNAs; the lncRNA GAS5 and the miRNA miR-34a in three of the most prevalent and high-incidence tumors in Egypt; hepatic, renal and brain cancer." (PMID 30289954, 2018).
brain tumors (2 papers, 2020 to 2022). "Two DElncRNAs, including EPB41L4A-AS1 and GAS5 have been associated with survival time of patients with brain tumors." (PMID 36119500, 2022). "In fact, there are very few studies on the role of GAS5 in brain tumors, in general." (PMID 33076450, 2020). "Since brain tumors are not easily manageable, there are not many reports on the connection of GAS5 and miRNAs." (PMID 33076450, 2020).
clear cell renal cell carcinoma (2 papers, 2020 to 2022). "Furthermore, studies in clear cell renal carcinoma and laryngeal squamous carcinoma have linked lower GAS5 expression to the advanced tumor stage and tumor size, respectively." (PMID 35736636, 2022). "GAS5 acted as a ceRNA to regulate hZIP1 by sponging miR-223 in the progression of clear cell renal cell carcinoma and targeting the GAS5/miR-223/hZIP1 axis served as a therapeutic strategy for patients." (PMID 32039833, 2020).
colorectal tumour (2 papers, 2014 to 2023). "We found significant differences in the expression levels of the GAS5-derived snoRNAs between paired samples of fresh frozen normal colorectal tissue and colorectal tumour from the same patient (P<0.01)." (PMID 24926850, 2014).
coronary atherosclerosis (2 papers, 2021 to 2024). Atherosclerosis of the coronary vasculature. "It is formerly conducted that long non-coding RNA growth arrest-specific 5 (GAS5) is involved in the process of coronary atherosclerosis (AS)." (PMID 33638792, 2021).
COVID-19 (2 papers, 2022 to 2025). A disease caused by infection with severe acute respiratory syndrome coronavirus 2. "The lncRNA GAS5 regulates ACE2 expression via miR-200c-3p and is potentially associated with the reduction of ARDS mortality in COVID-19 patients." (PMID 36204652, 2022). "Four lncRNAs, MALAT1, NEAT1, TUG1 and GAS5 are predicted as potential therapeutic targets in COVID-19." (PMID 36204652, 2022). "Finally, we predict the possible therapeutic targets of four lncRNAs, MALAT1, NEAT1, TUG1, and GAS5, in COVID-19." (PMID 36204652, 2022). "Based on existing research, the expression of lncRNA GAS5 is downregulated in COVID-19." (PMID 36204652, 2022). "Studies have shown that downregulation of lncRNA GAS5 expression reduces the expression of ACE2 by regulating the expression of miR-200c-3p, thus preventing the occurrence of ARDS lung injury, and reducing the chance of death in COVID-19 patients caused by ARDS." (PMID 36204652, 2022). "The observed upregulation of GAS5, NORAD, BISPR, and NEAT1 in dRNA-seq of infected Calu-3 cells (1.03- and 1.11-fold) is consistent with upregulation of these lncRNAs in COVID-19 patients (1.05- and 1.17-fold) in the two datasets (GSE171110 and GSE157103)." (PMID 41267684, 2025). "The upregulation observed of GAS5, NORAD, BISPR, and NEAT1 in dRNA-seq of infected Calu-3 cells (between 1.03- and 1.11-fold) is consistent with upregulation of these lncRNAs in COVID-19 patients (1.05- and 1.17-fold) in the two datasets (GSE171110 and GSE157103)." (PMID 41267684, 2025).
dementia (2 papers, 2020 to 2023). Loss of intellectual abilities interfering with an individual's social and occupational functions. "In summary, the study demonstrates that GAS5 contributes to pathways associated with neurodegeneration and NPC86 has tremendous therapeutic potential to prevent the advent of neurodegenerative diseases and dementias." (PMID 36609440, 2023). "The role of lncRNA GAS5 in atherogenesis in DS patients deserves elucidation but we cannot exclude that lncRNA GAS5 dysregulation may play a role, furthermore it could also be assumed that the same mechanism may affect early dementia in DS patients." (PMID 32624686, 2020).
demyelination (2 papers, 2017 to 2019). "Transplanting GAS5-downregulated microglia into the lateral ventricles of EAE mice could promote remyelination, similar to a lysolecithin-induced demyelination model." (PMID 30967783, 2019).
Gestational Diabetes Mellitus (2 papers, 2022 to 2024). "The goal of this work was to look at the expression and probable role of exosomal long noncoding RNA (lncRNA) GAS5 in gestational diabetes mellitus (GDM), as well as forecast the importance of its interaction with neuropeptides in the progression of the disease." (PMID 35178132, 2022).
HIV-1 infection (2 papers, 2020 to 2023). The type species of lentivirus and the etiologic agent of acquired immunodeficiency syndrome (AIDS). "Growth-arrest-specific transcript 5 (GAS5) is downregulated upon HIV-1 infection, which favors replication as GAS5 acts as a competing RNA, inhibiting the role of miR-873." (PMID 36674541, 2023). "Both GAS5 and NRON were previously shown to be downregulated during HIV-1 infection, which led to increased viral replication." (PMID 36674541, 2023). "GAS5 and NRON are known to be downregulated upon HIV-1 infection in cell line experiments." (PMID 36674541, 2023).
metastatic disease (2 papers, 2020 to 2021). "However, we observed significant differences in expression levels of GAS5 between HNSCC patients and healthy volunteers, as well as between HNSCC patients—locally advanced and recurrent and/or metastatic disease compared to non-cancer." (PMID 32947877, 2020).
myasthenia gravis (2 papers, 2022). Myasthenia gravis (MG) is a rare, clinically heterogeneous, autoimmune disorder of the neuromuscular junction characterized by fatigable weakness of voluntary muscles. "Furthermore, GAS5 and IL-10 mRNA levels in myasthenia gravis patients’ peripheral blood mononuclear cells (PBMCs) were significantly lower than in healthy controls." (PMID 36310591, 2022). "Chi‐squared test analysis showed that GAS5 levels were closely correlated with quantitative myasthenia gravis (QMG) score, MGII, and mean anti‐AChR titer, but not with age at onset and thymic abnormalities." (PMID 34936242, 2022).
Mycoplasma pneumoniae pneumonia (2 papers, 2022). Interstitial pneumonia caused by extensive infection of the lungs (lung) and bronchi, particularly the lower lobes of the lungs, by mycoplasma pneumoniae in humans. "The aim of the study was to explore the serum expression of long noncoding RNA (lncRNA) growth arrest-specific transcript 5 (GAS5) in Mycoplasma pneumoniae pneumonia (MPP) and its effect on lipid-associated membrane proteins (LAMPs)-induced apoptosis and inflammation." (PMID 36034211, 2022).
Myocardial fibrosis (2 papers, 2024). "METTL3 facilitates mitochondrial fission by augmenting the methylation of lncRNA GAS5 to induce myocardial fibrosis." (PMID 38405130, 2024). "And the overexpression of GAS5 inhibited the myocardial fibrosis and the NLRP3 inflammasome activation." (PMID 38561456, 2024). "To study the effects of GAS5 on myocardial fibrosis in vivo, we overexpressed GAS5 in mice and found that GAS5 did significantly elevate the pumping function of mice hearts treated with Isoprenaline (ISO)." (PMID 38561456, 2024). "Isoprenaline (ISO) was given subcutaneously to the male C57BL/6 mice to induce myocardial fibrosis and the AAV9 vectors were randomly injected into the left ventricle of each mouse to overexpress GAS5." (PMID 38561456, 2024). "The mir-217 mimics offset this effect of GAS5 on myocardial fibrosis, pyroptosis and SIRT1, and the mir-217 inhibitor enhanced all these effects of GAS5." (PMID 38561456, 2024). "Therefore we hypothesized that GAS5 could regulate the downstream target gene SIRT1 via mir-217 and subsequently inhibit myocardial fibrosis." (PMID 38561456, 2024).